IGF2BP2 (insulin like growth factor 2 mRNA binding protein 2)
Diseases named in the same sentence as IGF2BP2 in open-access papers (continued):
Sharing a sentence is not in itself a finding about the gene and the disease.
colorectal cancer (continued). "For instance, circNSUN2 can assemble into a complex with high mobility group A (HMGA2) mRNA and insulin-like growth factor 2 mRNA-binding protein 2 (IGF2BP2) to stabilize mRNA, triggering EMT and enhancing the aggressiveness of colorectal cancer (CRC)." (PMID 39120276, 2024). "LncRNA LINRIS promotes aerobic glycolysis in an m6A-mediated manner, and LINRIS knockdown decreases the downstream effects of IGF2BP2, especially MYC-induced glycolysis in colorectal cancer (CRC) cells." (PMID 38560499, 2024). "Insulin-like growth factor 2 mRNA-binding protein 2 (IGF2BP2) can preserve the stability of TFRC mRNA through m6A modifications, thereby increasing TFRC protein levels in colorectal cancer (CRC) cells and facilitating the growth of CRC." (PMID 38602575, 2024). "IGF2BP2 recognizes m6A in the CDS region of SOX2 and prevents its degradation, thereby contributing to the development and incidence of colorectal cancer." (PMID 38384328, 2024). "For example, LINC00920 blocked the ubiquitination of IGF2BP2 and maintained the MYC‐mediated glycolysis process in colorectal cancer." (PMID 35789547, 2023). "IGF2BP2 stabilizes MSX1 and JARID2 transcripts in an m6A-dependent manner, regulating cell migration and survival in colorectal cancer." (PMID 37280679, 2023). "In colorectal cancer, METTL3 cooperates with IGF2BP2 to increase the stability of SOX2 RNA, which promotes the transcription of MYC and enhances the self-renewal and proliferation of tumor cells." (PMID 37996892, 2023). "In colorectal cancer, circQSOX1 is methylated under the action of METTL3, and its stability is improved after binding with IGF2BP2." (PMID 37582735, 2023). "We used the HCT116 colorectal carcinoma cell line that has low levels of IGF2BP1, but high IGF2BP2 expression." (PMID 37582618, 2023). "For instance, the lncRNA LINRIS blocks the ubiquitination of K139 in IGF2BP2 and prevents its degradation through the autophagy-lysosomal pathway, thus maintaining MYC-mediated glycolysis and promoting the proliferation of colorectal cancer cells." (PMID 35299748, 2022). "The study on colorectal cancer revealed that LncRNA LINRIS enhanced the stability of IGF2BP2, which increased the binding of IGF2BP2 to m6A-modified MYC." (PMID 36358799, 2022). "In colorectal cancer, the LINC00460/DHX9/IGF2BP2 complex promotes proliferation and differentiation by stabilizing HMGA1 mRNA, depending on m6A modification." (PMID 36358799, 2022). "proved that METTL3 upregulates SOX2 expression through IGF2BP2 to recognize and increase the stability of SOX2 mRNA and promote colorectal carcinoma cell self-renewal, increase stem cell frequency and promote migration in a m6A-dependent manner." (PMID 35299748, 2022). "During the progression of colorectal cancer, LINRIS prevents K139 ubiquitination of IGF2BP2, thereby maintaining its stability." (PMID 34705667, 2021). "For example, IGF2BP2 was reported to be stabilized by lncRNA LINRIS, in turn promoting colorectal cancer." (PMID 34608837, 2021). "In colorectal cancer, lncRNA LINRIS increases aerobic glycolysis by stabilizing IGF2BP2 protein and blocking K139 ubiquitination of IGF2BP2." (PMID 32564010, 2020). "The m6A “writers” METTL3 and m6A “readers” IGF2BP2/3 were found to participate in the methylation of VEGFA to prevent mRNA degradation, and to promote angiogenesis in colorectal cancer by mimicking the formation of the PI3K/AKT/mTOR and ERK1/2 signaling pathways." (PMID 40316995, 2025). "In patients with colorectal cancer (CRC), METTL3 enhances the stability of hexokinase 2 (HK2) and glucose transporter GLUT1 mRNAs by interacting with their 3′UTR regions, with the stability of HK2 and GLUT1 being mediated by IGF2BP2 and IGF2BP3, respectively." (PMID 40428320, 2025). "Although there are currently no commercial inhibitors of IGF2BP2, a few reports recently identified some small-molecule IGF2BP2 inhibitors in colorectal cancer and T-cell acute lymphoblastic leukemia." (PMID 38281999, 2024).
colorectal cancer (continued). "For instance, circNSUN2 forms a ternary complex with IGF2BP2 and high mobility group A (HMGA2) mRNA in the cytoplasm which stabilizes mRNA, and then upregulation of HMGA2 induces epithelial-mesenchymal transition and enhances colorectal cancer aggressiveness." (PMID 38724502, 2024). "M6A-modified circNSUN2 binds YTHDC1 (YTH domain-containing protein 1) and promotes its exit from the nucleus, further binding IGF2BP2 (lnsulin-like growth factor 2 mRNA-binding protein 2), which stabilizes HMGA2 (high mobility group AT-hook 2) mRNA, thus promoting colorectal cancer liver metastasis." (PMID 38329551, 2024). "Additionally, the interaction between circNSUN2 and IGF2BP2 increases the stability of HMGA2 mRNA, leading to the promotion of liver metastasis in colorectal cancer." (PMID 38216996, 2024). "By generating the RNA–protein ternary complexes of circNSUN2/IGF2BP2/HMGA2 and enhancing HMGA2 mRNA stability, circNSUN2 could facilitate the metastasis of colorectal cancer to the liver." (PMID 38102645, 2023). "The formation of LINC00460/IGF2BP2/DHX9 complex reinforces HMGA1 mRNA stability in an m6A-dependent manner, promoting epithelial-mesenchymal transition (EMT), tumor growth, and metastasis in colorectal cancer." (PMID 37280679, 2023). "In colorectal cancer, overexpression of the m6A reader IMP2 (IGF2BP2) stabilizes the ZFAS1/OLA1 axis, thereby increasing OLA1 recruitment, ATP hydrolysis, and glycolysis; activating the Warburg effect; and enhancing cancer cell proliferation and colony formation." (PMID 36525280, 2023). "In concert with IGF2BP2, METTL3 promotes m6A modification of the SOX2 CDS region to inhibit SOX2 RNA degradation, which increases the protein content of intracellular SOX2 and induces colorectal cancer metastasis." (PMID 37996892, 2023). "For example, circNSUN2, an abnormally expressed circRNA in colorectal carcinoma (CRC) tissues, could regulate the stability of HMGA2 mRNA by binding to IGF2BP2, resulting in cancer progression." (PMID 37592296, 2023). "In addition, circNSUN2 can bind to IGF2BP2 and HMGA2, forming the circNSUN2/IGF2BP2/HMGA2 RNA–protein ternary complex, which contributes to promoting colorectal carcinoma metastasis." (PMID 37723588, 2023). "Similarly, IGF2BP2 stabilizes the HK2 and SLC2A1 mRNAs, and accelerates glycolytic metabolism and cell proliferation in colorectal cancer." (PMID 35299748, 2022). "In colorectal cancer, METTL3 promotes glycolysis metabolism to drive tumorigenesis, mechanistically, METTL3 mediates m6A modification to enhance the expressions of HK2 and SLC2A1 through IGF2BP2/3-dependent mRNA stability function." (PMID 35541906, 2022). "METTL3 has been found to guarantee the stability of hexokinase 2 (HK2) and solute carrier family 2 member 1 (SLC2A1) via an m6A-insulin-like growth factor 2 mRNA-binding protein 2 (IGF2BP2)/3-dependent pathway, contributing to the tumorigenesis of colorectal cancer (CRC)." (PMID 35804965, 2022). "In colorectal cancer, the overexpression of m6A reader IMP2 (IGF2BP2) can stabilize ZFAS1/OLA1 axis, which increases the recruitment of OLA1, ATP hydrolysis and glycolysis, activates Warburg effect, and enhances cell proliferation and colony formation of cancer cells." (PMID 35022030, 2022). "In an IGF2BP2-dependent manner, METTL3 increases the progression of colorectal cancer." (PMID 36358799, 2022). "LINC00460 directly interacts with IGF2BP2 and DHX9 to assist the recognition protein IGF2BP2 to recognize and stabilize HMGA1 mRNA, enhance the protein expression of HMGA1, and promote the proliferation and metastasis of colorectal cancer." (PMID 33926508, 2021). "Previous studies have shown that METTL3 methylated SOX2 transcripts, subsequently recognized by the specific m6A “reader” and insulin-like growth factor 2 mRNA-binding protein 2 (IGF2BP2), to maintain SOX2 stability and promote colorectal carcinoma progression." (PMID 34858987, 2021).
colorectal cancer (continued). "In colorectal cancer, IGF2BP2 can recognize m6A sites in the CDS region of SOX2, enhancing its stability and preventing its degradation, leading to the occurrence and development of colorectal cancer." (PMID 33363011, 2020). "Additionally, IGF2BP2 decreases MTA1 expression in the absence of FTO, indicating that FTO and IGF2BP2 control MTA1 expression in colorectal cancer via methylation." (PMID 40919129, 2025). "Additionally, IGF2BP2 could stabilize the mRNA of HMGA1 and protein expression, promoting colorectal cancer progression." (PMID 38102645, 2023). "Studies have shown that the lncRNA LINRIS could inhibit the degradation of the autophagy-lysosome pathway-dependent m6A reader IGF2BP2 by binding to the K139 ubiquitination site of IGF2BP2, maintaining MYC-mediated glycolysis and colorectal cancer cell proliferation." (PMID 36632456, 2023). "In colorectal cancer, long non-coding RNA LINRIS blocks K139 ubiquitination of IGF2BP2, stabilizes the expression level of IGF2BP2 through autophagy lysosomal pathway, and promotes c-Myc mediated glycolysis through LINRIS-IGF2BP2-c-Myc axis, thereby promoting the progression of colorectal cancer." (PMID 35022030, 2022). "Similarly, IGF2BP2 recognizes the coding sequence (CDS) regions of transcription factor SOX2 and protects it from degradation in m6A- mediated manner, which facilitates tumorigenesis and metastasis in colorectal cancer." (PMID 35541906, 2022). "For example, m6A modification stabilizes and promotes the expression of SOX2 through IGF2BP2-dependent pathways and increases the expression of its downstream targets (CCND1, MYC, and POU5F1), which in turn promotes the occurrence, invasion, and metastasis of colorectal cancer." (PMID 33926508, 2021). "On the contrary, YTHDF3 reversibly and selectively binds to the m6A modified GAS5 to trigger the decay of GAS5, thus promoting the progress of CRC and forming a negative feedback loop; In colorectal cancer, lncRNA LINRIS (Long Intergene Non-Coding RNA For IGF2BP2 Stability) is highly expressed." (PMID 35070987, 2021).
pancreatic cancer (80 papers, 2012 to 2026). "The second member of the IGF2BP family, namely IGF2BP2, was found to be overexpressed in pancreatic cancer tissues as well, where it has been associated with significantly shorter OS." (PMID 40427100, 2025). "Upregulation of IGF2BP2 expression is associated with poor prognosis in patients with pancreatic cancer, and inhibiting IGF2BP2 impedes cell proliferation." (PMID 34246319, 2021). "In pancreatic cancer, IGF2BP2 has been implicated as a reader to regulate lncRNA DANCR, leading to cell viability and proliferation, and stemness-like properties." (PMID 35047491, 2021). "A recent study revealed that IGF2BP2 was significantly overexpressed in human PanIN 81, which is associated with a high risk of developing pancreatic cancer." (PMID 34239358, 2021). "IGF2BP2 overexpression is associated with worse OS in pancreatic cancer patients and promotes growth of pancreatic cancer cells by activating the PI3K/Akt signaling pathway." (PMID 33795529, 2021). "Here we showed that upregulation of IGF2BP2 is associated with poor outcomes of pancreatic cancer patients and suppression of IGF2BP2 inhibits cell proliferation." (PMID 31804607, 2020). "In summary, we found that upregulation of IGF2BP2 in pancreatic cancer is associated with poor clinical outcomes." (PMID 31804607, 2020). "In the present study, we found that IGF2BP2 is highly expressed in pancreatic cancer, and upregulation of IGF2BP2 is associated with poor prognosis of pancreatic cancer patients." (PMID 31804607, 2020). "Based on the TCGA dataset, we found that IGF2BP2 was effective in stratifying pancreatic cancer patients into high and low-risk of death groups." (PMID 31852504, 2019). "A recent study on pancreatic cancer also demonstrated that upregulation of IGF2BP2 predicted a poor prognosis and was associated with metastasis." (PMID 31852504, 2019). "Overexpression of IGF2BP2 in pancreatic cancer patients is associated with poor prognosis." (PMID 40271153, 2025). "IGF2BP2 is also an m6A reader and is closely associated with the prognosis of pancreatic cancer." (PMID 37910780, 2023). "In addition, increased IGF2BP2 expression was associated with a poor prognosis in pancreatic cancer." (PMID 34239358, 2021). "In addition, upregulation of IGF2BP2 was associated with poor prognosis in patients with pancreatic cancer." (PMID 32398132, 2020). "In addition, the present study identified that genomic alterations and loss of miR-141 partly contribute to IGF2BP2 overexpression and facilitate the oncogenic effect of IGF2BP2 in pancreatic cancer." (PMID 31852504, 2019). "Notably, IGF2BP2 mRNA expression level was significantly associated with IGF2BP2 CNV, indicating that genomic amplification may be one of the underlying mechanisms for the abnormal expression of IGF2BP2 in human pancreatic cancer." (PMID 31852504, 2019). "TCGA and Gene Expression Omnibus (GEO) database analysis revealed that IGF2BP2 is involved in the prognosis of pancreatic cancer and is a pancreatic cancer marker." (PMID 40448344, 2025). "In gastric and pancreatic cancers, IGF2BP2 stabilizes oncogenic mRNAs and promotes glutamine metabolism, suggesting similar roles in the aggressive behavior seen in cancers like COAD and KIRP." (PMID 40565233, 2025). "Beyond boosting histone lactylation and fuelling pancreatic cancer cell growth, IGF2BP2 also promotes the M2 polarization of TAMs, playing a key role in the progression of pancreatic cancer." (PMID 41190507, 2025). "CircMYO1 is upregulated in pancreatic cancer and stabilizes m6A‐modified PD‐L1 mRNA with IGF2BP2 to upregulate PD‐L1 expression, promoting immune escape." (PMID 40448344, 2025). "In pancreatic cancer, IGF2BP2 promotes cancer cell proliferation and metastasis through activation of the PI3K–Akt signaling pathway." (PMID 40469197, 2025).
pancreatic cancer (continued). "Previous studies have demonstrated that IGF2BP2 plays an oncogenic role in the development and progression of pancreatic cancer, breast cancer, and other diseases." (PMID 38778089, 2024). "Overexpression of some genes related to insulin signaling, including IGF2BP2, has been reported in pancreatic cancer." (PMID 38468402, 2024). "In pancreatic cancer, IGF2BP2, a reader of m6A, enhances stem cell properties and carcinogenesis by stabilizing DANCR RNA and regulating the expression of lncRNA DANCR." (PMID 38028627, 2023). "In pancreatic cancer, IGF2BP2 facilitates cancer occurrence and promotes stem-cell-like properties by regulating DANCR as an m6A reader." (PMID 36358799, 2022). "IGF2BP2, overexpressed in pancreatic cancer tissues, boosts pancreatic cancer cells’ growth through the activation of the PI3K/Akt signaling pathway in vitro and in vivo." (PMID 35014946, 2022). "In pancreatic cancer, insulin-like growth factor 2 mRNA-binding protein 2 (IGF2BP2), which represents a unique family of m6A readers, promotes cell proliferation and stemness maintenance of CSCs." (PMID 35449193, 2022). "As for IGF2BP2, it was reported that IGF2BP2 was differentially expressed in pancreatic cancer, and its upregulation promotes cancer cells’ growth through stimulating the PI3K/Akt pathway." (PMID 34420511, 2022). "For example, results have shown that IGF2BP2 can promote the progression of pancreatic cancer by activating this pathway." (PMID 35129592, 2022). "Many studies have shown that IGF2BP2 is abnormally expressed in pancreatic cancer, liver cancer, thyroid cancer, and other malignant tumors." (PMID 35129592, 2022). "For example, in pancreatic cancer, IGF2BP2 as Reader recognizes m6A-modified lncRNA DANCR, which promotes the progression of pancreatic cancer by improving the stability of DANCR." (PMID 35070987, 2021). "Overexpression of IGF2BP2 promotes the progression of pancreatic cancer cells, which can be treated as a marker for the diagnosis and prognosis of pancreatic cancer." (PMID 34345216, 2021). "Previously, an interaction between IGF2BP2 and DANCR has been implicated in pancreatic cancer, where IGF2BP2 promotes DANCR expression and DANCR contributes to tumorigenesis and cancer cell growth." (PMID 35141227, 2021). "For example, up-regulating IGF2BP2 expression can promote pancreatic cancer cell proliferation through activating PI3K/Akt signaling pathway." (PMID 34345216, 2021). "For example, the up-regulated IGF2BP2 promotes pancreatic cancer cell proliferation by activating the PI3K/Akt signaling pathway." (PMID 34809621, 2021). "For instance, IGF2BP2 promotes proliferation and stemness-like properties of pancreatic cancer cells by binding and stabilizing m6A modified DANCR RNA." (PMID 33568150, 2021). "Genomic amplification and silencing of miR-141 also contribute to IGF2BP2 activation; opening promise molecular targets in pancreatic tumors." (PMID 35095996, 2021). "Our recent study demonstrated that IGF2BP2 stabilizes DANCR RNA to confer the stemness of pancreatic cancer cells." (PMID 34809621, 2021). "Although a recent study in pancreatic cancer deliberated that IGF2BP2 served as a reader for m6A-modified DANCR and stabilized DANCR RNA comprehensive investigation is needed to explore the tumorigenesis and progression of CRC." (PMID 34743750, 2021). "For example, Up-regulation of IGF2BP2 promotes pancreatic cancer proliferation by activating the PI3K/Akt signaling pathway, enhances liver cancer growth through an m6A-FEN1-dependent mechanism." (PMID 33748145, 2021). "The lncRNA DANCR and IGF2BP2 (reader) have been proven to synergistically promote the pathogenesis of pancreatic cancer." (PMID 34238292, 2021). "For example, in pancreatic cancer, up-regulation of IGF2BP2 promotes tumor cell proliferation by involved the PI3K/Akt signaling pathway activation." (PMID 34345216, 2021).